RECK (reversion inducing cysteine rich protein with kazal motifs)
Diseases named in the same sentence as RECK in open-access papers (continued):
Sharing a sentence is not in itself a finding about the gene and the disease.
oral squamous cell carcinoma (3 papers, 2008 to 2020). "Our findings implied that the hypermethylation of RECK is associated with a low level of mRNA expression in oral squamous cell carcinoma cell lines." (PMID 18665171, 2008). "In the present study, we investigated the effects of epigallocatechin-3-gallate (EGCG), a major polyphenol in green tea, on the methylation status of the RECK gene and cancer invasion in oral squamous cell carcinoma cell lines." (PMID 18665171, 2008). "In the present study, we determined the effects of EGCG treatment on the methylation status and expression level of the RECK gene in human oral squamous cell carcinoma cell lines." (PMID 18665171, 2008). "EGCG treatment of human oral squamous cell carcinoma cell lines partially reversed the hypermethylation status of the RECK gene, a matrix metalloproteinase inhibitor, and increased RECK expression, consequently, extracellular matrix degradation was inhibited and cell invasion was suppressed." (PMID 30627525, 2018).
sarcoma (3 papers, 2010 to 2023). A usually aggressive malignant neoplasm of the soft tissue or bone. "Hence, DSF could recapitulate some effects of RECK-transgene on the morphology and behavior of these sarcoma cells." (PMID 21304177, 2010). "Our findings also shed light on mechanisms by which these sarcoma cells acquired metastatic potential and how DSK638 activates RECK expression and suppresses tumor metastasis." (PMID 35149728, 2022). "A previous study showed that RECK does not affect the growth of sarcoma cells in xenograft experiments." (PMID 37712427, 2023).
ameloblastoma (2 papers, 2009 to 2019). The most common odontogenic tumor, arising from the epithelial component of the embryonic tooth and usually affecting the molar-ramus region of the mandible or maxilla. "RECK protein expression was negatively associated with MMP-2 protein expression in ameloblastoma (r = -0.431, P < 0.01)." (PMID 19995435, 2009). "In ameloblastoma, protein expression in RECK and MMP-2 were inversely proportional (r = -0.431, P < 0.01), but mRNA expression of RECK and MMP-2 were not correlated (r = 0.367, P > 0.05)." (PMID 19995435, 2009). "Relative expression levels of RECK mRNA were significantly lower in ameloblastoma than in KCOT (P < 0.01), but significantly higher for MMP-2 mRNA (P < 0.01)." (PMID 19995435, 2009). "Therefore, this study investigated the combinatorial role and association of RECK and MMP-2 in ameloblastoma." (PMID 19995435, 2009). "RECK may participate in the invasion, recurrence and malignant transformation of ameloblastoma by regulating MMP-2 at the post-transcriptional level." (PMID 19995435, 2009). "However, few reports have delineated the combinatorial role and association of RECK and MMP-2 in ameloblastoma." (PMID 19995435, 2009). "Our results indicated that the protein expression and the transcriptional levels of RECK were sequentially lower or absent as odontogenic tumor cells increased in aggressiveness, indicating that RECK expression levels may be correlated with clinical outcomes in ameloblastoma." (PMID 19995435, 2009). "The aim of this study was to characterize the relationship between RECK and MMP-2 expression and the clinical manifestation of ameloblastoma." (PMID 19995435, 2009). "Immunohistochemistry and reverse transcription-polymerase chain reaction (RT-PCR) were employed to detect the protein and mRNA expression of RECK and MMP-2 in keratocystic odontogenic tumor (KCOT), ameloblastoma and ameloblastic carcinoma." (PMID 19995435, 2009). "In summary, lower or no expression of RECK and increased expression of MMP-2 may be associated with worse clinical outcomes in ameloblastoma, and RECK may help modify the behavior of ameloblastomas by regulating MMP-2 at the post-transcriptional level." (PMID 19995435, 2009). "Low or no RECK expression and increased MMP-2 expression may be associated with negative clinical findings in ameloblastoma." (PMID 19995435, 2009). "RECK mRNA expression was significantly lower in ameloblastoma than in KCOT (P < 0.01), lower in recurrent ameloblastoma than in primary ameloblastoma, and was negative in ameloblastic carcinoma." (PMID 19995435, 2009). "RECK mRNA was detected in all KCOT and ameloblastoma samples, but not in either ameloblastic carcinoma sample." (PMID 19995435, 2009).
asthma (2 papers, 2016 to 2023). "Among the differentially co-expressed genes, eight were previously linked to asthma in genome- (MRPL14, ASB3, RHOBTB2) and epigenome-wide (CLC, EPS15, GPI, SSCRB4, STRN4) association studies and five were mentioned in the literature in the context of asthma (SLC19A1, MAEA, CLC, ATP1B1, and RECK)." (PMID 36835202, 2023).
cholangiocarcinoma (2 papers, 2021 to 2023). A carcinoma that arises from the intrahepatic biliary tree (intrahepatic cholangiocarcinoma) or from the junction, or adjacent to the junction, of the right and left hepatic ducts (hilar cholangiocarcinoma). "Within the context of the liver, RECK’s role was assessed in the pathogenesis of HCC and cholangiocarcinoma (CCA)." (PMID 34745017, 2021).
Cirrhosis (2 papers, 2021). A chronic disorder of the liver in which liver tissue becomes scarred and is partially replaced by regenerative nodules and fibrotic tissue resulting in loss of liver function. "It is unknown whether RECK is already downregulated or silenced in NAFLD, causing exacerbation of symptoms, including development and progression towards NASH, cirrhosis, and HCC." (PMID 34745017, 2021). "It is also unclear whether RECK expression is altered prior to the formation of HCC in situations of NAFLD or cirrhosis." (PMID 34745017, 2021).
coronary artery disease (2 papers, 2021 to 2023). "We conducted a receiver operating characteristic analyses (ROC) to evaluate the potentiality of circulating RECK splice variants in identifying patients with stable coronary artery disease (CAD) from those who have an increased risk of developing myocardial event (AMI)." (PMID 34205376, 2021). "Anyway, the different regulation of Long and Short RECK splice variants in CTR subjects, CAD and AMI patients indicate that their expression level might be a good genomic biomarker of clinical outcome in coronary artery disease patients." (PMID 34205376, 2021).
diabetes (2 papers, 2018 to 2023). "Although the role of RECK deficiency in promoting angiogenesis and cardiac fibrosis has been reported previously, the influence of low RECK expression on renal injury and fibrosis in diabetes has not been investigated." (PMID 30060748, 2018).
endometrial adenocarcinoma (2 papers, 2022 to 2024). "The suppressive effect of miR200b on RECK gene expression was confirmed in the 12Z cell line, derived from a peritoneal endometriotic lesion, and the Ishikawa cell line, originating from endometrial adenocarcinoma." (PMID 39519143, 2024). "Furthermore, we employ the 12Z cell line, derived from a peritoneal endometriotic lesion, and the Ishikawa cell line, originating from endometrial adenocarcinoma to identify RECK as a direct target of miR200b." (PMID 39519143, 2024). "After MDGA1 was removed, the remaining candidate hub genes (RECK, CFL2, TGFBR3, TPM2, and C10ORF91) affecting the survival rate of endometrial adenocarcinoma in the MEbrown module and MEturquoise module were selected." (PMID 35123404, 2022).
endometriosis (2 papers, 2024 to 2025). The growth of functional endometrial tissue in anatomic sites outside the uterine body. "Wnt protein binding (GOMF) was a significant pathway in our gene set analyses, with five genes overlapping with our biologically-implicated endometriosis gene set: CTHRC1 (mSMR), FZD6 (fibroblast-eSMR), PTPRO (fibroblast-, ovary-, and whole blood-TWAS), RECK (fibroblast-sSMR), and TRABD2A (mSMR)." (PMID 41377979, 2025). "The biological function of RECK strongly suggests that it may play a part in the pathogenesis of endometriosis." (PMID 39519143, 2024). "While endometriosis is characterized by a higher production of MMPs, followed by an increased invasiveness of endometriotic cells, an elevated RECK expression may represent a regulatory feedback mechanism, opening up interesting new search routes." (PMID 39519143, 2024). "The described effect of miR200b on RECK, together with the aberrant expression of both genes in endometrioma, may help to understand the role played by the tissue remodeling system in the pathogenesis of endometriosis." (PMID 39519143, 2024). "The demonstrated effect of miR200b on RECK gene expression, together with the altered expression of both genes in endometrioma, may help to recognize the role played by the inhibitors of metalloproteases in the pathogenesis of endometriosis." (PMID 39519143, 2024). "The present study demonstrates that the expression of the RECK gene is elevated in endometriotic lesions when compared to control endometrium from women without endometriosis." (PMID 39519143, 2024). "Our study demonstrates that RECK expression is higher in endometriotic tissue when compared to the control endometrium, e.g., derived from women without endometriosis." (PMID 39519143, 2024). "Similarly, it is not clear what is the meaning of the increased RECK expression in view of the pathogenesis of endometriosis." (PMID 39519143, 2024).
esophageal squamous cell carcinoma (2 papers, 2016 to 2022). Esophageal squamous cell carcinoma (ESCC) is a type of esophageal carcinoma (EC) that can affect any part of the esophagus, but is usually located in the upper or middle third. "RECK is downregulated in esophageal squamous cell carcinoma (ESCC) and associated with a poor survival in ESCC." (PMID 35309509, 2022).
Hepatic fibrosis (2 papers, 2021 to 2023). The presence of excessive fibrous connective tissue in the liver. "Although the role of RECK in myocardial fibrosis has been thoroughly studied, its role in the development of hepatic fibrosis is still poorly understood." (PMID 38139236, 2023). "Due to RECK’s inhibition of ADAM17 and consequent downregulation in EGFR signaling, it is plausible that sustaining or inducing RECK has the potential to prevent or even reverse hepatic fibrosis seen in NASH." (PMID 34745017, 2021). "Therefore, we further examined the literature to determine whether RECK was found to be involved in pathways and physiological processes leading up to and including progression of NASH and liver fibrosis." (PMID 34745017, 2021).
invasive breast carcinoma (2 papers, 2016 to 2020). A carcinoma that infiltrates the breast parenchyma. "On chromosome 9 are located the tumor suppressor genes CDKN2A, PIPSK1B, BTEB1, RECK and BAG1, the latter associated with antiapoptotic functions and overexpressed in invasive breast carcinomas." (PMID 27325915, 2016).
nasopharyngeal carcinoma (2 papers, 2012 to 2023). A carcinoma arising from the nasopharyngeal epithelium. "In addition, using a nasopharyngeal carcinoma cellular model Liu and co-workers showed that the Epstein-Barr-Virus latent protein 1 (LMP1) can down-regulate RECK expression, and that Sp1 binding site on RECK's promoter is essential for this effect." (PMID 22438955, 2012).
osteoporosis (2 papers, 2017 to 2023). A condition of reduced bone mass, with decreased cortical thickness and a decrease in the number and size of the trabeculae of cancellous bone (but normal chemical composition), resulting in increased fracture incidence. "MiR-21 overexpression reversed osteoporosis by targeting RECK and miR-34a prevented osteoporosis by inhibiting osteoclastogenesis via targeting Tgif2." (PMID 28471397, 2017).
pituitary adenomas (2 papers, 2009 to 2024). "Bioinformatics was used to analyze pituitary adenoma-related genes and screen new targets related to RECK and miRNA." (PMID 38686051, 2024). "In summary, this study investigated the molecular mechanism by which miR-200b-3p regulates the progression of pituitary adenoma through the negative regulation of RECK." (PMID 38686051, 2024). "The expression of RECK in pituitary adenoma tissues was lower than that in neighboring tissues." (PMID 38686051, 2024).
prostate (2 papers, 2012 to 2021). "RECK and ZEB2 are involved in cancer metastasis and are also associated with urogenital cancer networks." (PMID 33987019, 2021). "Experimental studies must be performed in order to show the precise role of miR-21 and MMP and its regulators, specially RECK in prostate carcinogenesis." (PMID 22642976, 2012).
renal carcinoma (2 papers, 2013 to 2021). A carcinoma arising from the epithelium of the renal parenchyma or the renal pelvis. "In the recent work, we found that endothelial cells co-cultured with renal carcinoma cells significantly reduced RECK expression under chemical hypoxia." (PMID 34695807, 2021). "RECK expression in renal carcinoma did not differentiate according to survival time, either in the whole group of 387 cases or in the subgroup of 181 pN0/M0 cases." (PMID 24131772, 2013).
renal cell carcinoma (2 papers, 2013 to 2020). "We propose RECK down regulation in renal cell carcinoma to be an early event that facilitates tumor formation and progression." (PMID 24131772, 2013). "RECK strongly decreased in renal cell carcinoma compared to normal counterparts (Wilcoxon signed rank test, P < 0.001), and it discriminated tumor entities showing the highest expression in oncocytomas." (PMID 24131772, 2013). "Eight pairs of renal cell carcinoma and adjacent normal tissue presented the active glycosylated form of RECK migrating at 125 kDa and a lower RECK band of about 90 kDa." (PMID 24131772, 2013). "Due to our findings of RECK/EMMPRIN imbalance in urothelial bladder carcinoma, which could promote invasion processes, we decided to look not only at RECK, but also at the EMMPRIN counterpart in renal cell carcinoma." (PMID 24131772, 2013).
squamous cell carcinoma (2 papers, 2016 to 2017). A carcinoma arising from squamous epithelial cells. "Subsequently, down-regulated genes (FAS, PTPRB, MEOX2 and RECK) were considered where lower expression of the genes correlated with poor prognosis in lung adeno- but not so in squamous cell carcinoma patients." (PMID 29254206, 2017).
Stroke (2 papers, 2018 to 2023). Sudden impairment of blood flow to a part of the brain due to occlusion or rupture of an artery to the brain. "On the other hand, reversion‐inducing cysteine‐rich protein with Kazalmotifs (RECK) is one of the inhibitor of MT1‐MMP in other models, but whether RECK suppress the function of MT1‐MMP in stroke is not clear." (PMID 30035384, 2018). "A GPR124-selective WNT7 mutant (K190A) selectively activates β-catenin signaling via GPR124/RECK without stimulating FZD, and also exhibits activity in experimental stroke models." (PMID 37268690, 2023).
urothelial bladder carcinoma (2 papers, 2013 to 2021). "In a later study, this same author demonstrated similar behavior of tissue gene expression of MMP-9, TIMP-1, and RECK in patients with urothelial carcinoma of the bladder, with most patients overexpressing MMP-9 underexpressing TIMP -1 and RECK." (PMID 35097136, 2021).
ameloblastic carcinoma (1 paper, 2009). A rare, cytologically malignant ameloblastoma that may metastasize. "Immunoreactivity for RECK was detected in nearly all epithelial cells of KOCT, in central polyhedral cells of follicular ameloblastoma and in peripheral columnar cells of plexiform ameloblastoma, but not in ameloblastic carcinoma cells." (PMID 19995435, 2009).
and T-cell lymphomas (1 paper, 2013). "MT1-MMP, TIMP-1 and RECK mRNA levels were significantly higher in T-cell lymphomas than in B-cell lymphomas." (PMID 23641796, 2013). "When considering the tissue inhibitor RECK, statistically significant differences were observed between B-cell and T-cell lymphomas, and between T-cell lymphomas and healthy controls (p<0.05)." (PMID 23641796, 2013). "The expressions of MMP-9, MT1-MMP, TIMP-1 and RECK were significantly higher in HG T-cell lymphomas compared to HG B-cell lymphomas (p<0.05)." (PMID 23641796, 2013).
aortic stenosis (1 paper, 2020). Aortic valve stenosis is a aortic valve disease caused by the incomplete opening of the aortic valve. "For example, in patients with aortic stenosis (AS), myocardial and plasmatic miR-21 levels predicted collagen type I, collagen type III, and fibronectin expression by targeting RECK, PDCD4, and TGF-β-signaling factors." (PMID 33014530, 2020).
astrocytomas (1 paper, 2015). "Here, we focus on the isolation and characterization of RECK tumor and metastasis suppressor gene splice variants, their interaction with MMPs and the resulting impact in astrocytoma biology." (PMID 26431549, 2015). "In the present study, we report on the identification of two novel RECK gene splice variants, namely: RECK-B (1,548bp), and RECK-I (1,101bp), and the characteristics of their expression profiles in normal human tissues and astrocytoma of different grades (II–IV)." (PMID 26431549, 2015). "Canonical RECK expression decreases from grade II to higher-grade astrocytomas." (PMID 26431549, 2015). "The expression levels and profiles of these alternative RECK transcripts, as well as canonical RECK were determined in tissue samples of malignant astrocytomas of different grades and in a normal tissue RNA panel by qRT-PCR." (PMID 26431549, 2015). "We examined the mRNA expression profiles of RECK transcripts, as well as of MMPs reportedly inhibited by canonical RECK (MMP-2, -9 and -14), and of endogenous tissue inhibitors of MMPs (TIMP-1, TIMP-2, TIMP-3 and TIMP-4) in astrocytomas of different grades of malignancy." (PMID 26431549, 2015).
benign oncocytoma (1 paper, 2013). "Higher RECK levels could also contribute to decreasing malignancy up to the benign oncocytoma, but it would be considered as an early marker for malignancy due to the high percentage of RECK-negative tumors in our study." (PMID 24131772, 2013).
benign prostatic hyperplasia (1 paper, 2018). A non-cancerous nodular enlargement of the prostate gland. "Anti‐miRs increased expression of RECK mRNA and protein in HT1080 fibrosarcoma cells, but, decreased RECK mRNA and increased its protein in the benign prostatic hyperplasia cell line BPH‐1." (PMID 30035384, 2018).
brain tumors (1 paper, 2010).
cervical squamous cell carcinoma (1 paper, 2024). A squamous cell carcinoma arising from the cervical epithelium. "In a previous study, the levels of RECK expression were analyzed in samples from women with high-grade cervical lesions (CIN II/CIN III) and cervical squamous cell carcinoma (SCC)." (PMID 38612895, 2024).
cervical tumor (1 paper, 2024). "In this study, we demonstrated the effects of MRE21-1, MRE21-2, and MRE21-3 recognition sites on the downregulation of RECK gene expression mediated by miR-21 in human cervical tumor cells." (PMID 38612895, 2024).
cholesteatoma (1 paper, 2012). A pathologic process characterized by the proliferation of keratinizing squamous epithelium resulting in the accumulation of keratin and cells in the middle ear and/or mastoid. "It was observed here that the reversion-inducing cystein-rich protein with Kazal motifs RECK is significantly down-regulated in cholesteatoma." (PMID 23285167, 2012).
chordoma (1 paper, 2022). Chordomas are rare malignant tumors arising from embryonic remnants of the notochord in axial skeleton. "Other regulators of stemness, such as MYBL1 and RECK are also predicted targets for multiple upregulated miRNAs in our study, and, together with LCOR and YAP/TAZ may form a regulatory network maintaining the stem-cell phenotype in chordoma." (PMID 36033338, 2022).